CBX7 (chromobox 7)
Diseases named in the same sentence as CBX7 in open-access papers (continued):
Sharing a sentence is not in itself a finding about the gene and the disease.
lymphoma (11 papers, 2010 to 2024). A malignant (clonal) proliferation of B- lymphocytes or T- lymphocytes which involves the lymph nodes, bone marrow and/or extranodal sites. "CBX7 may cause the occurrence of lymphoma by enhancing stem cell self-renewal or increasing the replication potential of cancer stem cells." (PMID 34659360, 2021). "In hematopoietic cells, CBX7‐enforced self‐renewal eventually leads to lymphoma or leukemia development." (PMID 38426219, 2024). "CBX7 usually cooperates with C-MYC in the formation of aggressive lymphomas during lymphocyte genesis." (PMID 34659360, 2021). "In mouse models, the combination of MYC with CBX7 overexpression resulted in a faster lymphoma development." (PMID 35008680, 2021). "For example, CBX7 expression is upregulated in lymphomas and gastric tumors, but downregulated in malignancies such as colon, thyroid, pancreatic, and urothelial carcinomas." (PMID 24260522, 2013). "It was found that CBX7 expression was upregulated in lymphoma, but downregulated in some other human malignancies." (PMID 20723236, 2010). "CBX7-related assays included central serous chorioretinopathy, urothelial carcinoma, MIXED LINEAGE LEUKEMIA, carcinoma, transitional cell, lymphoma, follicular, and eosinophil count procedures." (PMID 37189494, 2023). "However, CBX7 does not regulate cancer progression alone, the long latency and incomplete penetrance observed after overexpression of CBX7 suggest that aberrant CBX7 expression is not sufficient for causing lymphoma." (PMID 34659360, 2021). "In contrast, CBX2, CBX7, and CBX8 have oncogenic potential in hematopoiesis as they promote the survival of leukemia and lymphoma cells." (PMID 38426219, 2024). "Recently developed inhibitors against CBX7 might restore the INK4A/ARF-axis in malignant cells and thus, prevent lymphoma cell proliferation." (PMID 35008680, 2021). "Furthermore, Cbx7‐KO mice do not develop lymphoma whereas Cbx7‐wild‐type mice do, indicating that Cbx7 has oncogenic potential and is able to push normal hematopoiesis toward lymphoma cell fate." (PMID 38426219, 2024).
glioblastoma (10 papers, 2010 to 2025). The most malignant astrocytic tumor (WHO grade IV). "In summary, our data suggest that CBX7 is frequently downregulated in glioblastoma and is significantly associated with poor prognosis in glioblastoma patients." (PMID 39988672, 2025). "Studies have reported that the downregulation of CBX7 in glioblastoma is caused by hypermethylation of its promoter, but the specific DNA methyltransferases (DNMTs) mediating CBX7 promoter hypermethylation have not been elucidated." (PMID 39988672, 2025). "Clinically, low levels of CBX7 expression are associated with poor prognosis in glioblastoma patients, increased self-renewal capacity, and enhanced proliferation of cancer cells." (PMID 39988672, 2025). "In summary, we show that downregulation of CBX7 in glioblastoma is caused by promoter hypermethylation that is mediated by DNMT1 and DNMT3A." (PMID 39988672, 2025). "Clinically, low levels of CBX7 are associated with poor prognosis and increased distant metastasis in glioblastoma patients, and this low expression is caused by methylation of the CBX7 promoter." (PMID 39988672, 2025). "In this study, through bioinformatics analysis, we found that CBX7 is the most significantly downregulated member of the CBX family in glioblastoma and is closely associated with the stem-like phenotype of glioblastoma cells." (PMID 39988672, 2025). "We examined the association between CBX7 expression and these glioblastoma subtypes and found that CBX7 expression varied among different subtypes and was significantly different from the normal group." (PMID 39988672, 2025). "Mutations in Cbx7 are correlated with increased glioblastoma multiforme tumor invasiveness." (PMID 36517477, 2022). "Cell growth experiments demonstrated that CBX7 overexpression significantly inhibited the growth of glioblastoma cell lines." (PMID 39988672, 2025). "In summary, CBX7 acts as a tumor suppressor by inhibiting the stem cell-like characteristics of glioblastoma." (PMID 39988672, 2025). "In this study, we report the regulatory function and mechanism of CBX7 in glioblastoma cells stemness." (PMID 39988672, 2025). "Subsequent functional experiments showed that CBX7 overexpression reduced clonogenicity and significantly decreased the migration and invasion potential of glioblastoma cells." (PMID 39988672, 2025). "To further determine the clinical significance of CBX7 in human glioblastoma, we performed immunohistochemistry (IHC) on a glioblastoma tissue microarray containing 180 tumor samples." (PMID 39988672, 2025). "Overall, our study highlights the critical role of CBX7 in regulating glioblastoma cell stemness and provides new insights into its potential as a therapeutic target and prognostic marker." (PMID 39988672, 2025). "Our findings indicate that CBX7 suppresses stem cell-like biological behaviors in glioblastoma by inhibiting the NF-κB signaling pathway." (PMID 39988672, 2025). "To determine the significance of CBX7 in human glioblastoma, we used a 3D culture method to derive primary cells from patient-derived glioblastoma tissue." (PMID 39988672, 2025). "Overall, our findings reveal that DNA methyltransferases (DNMT1 and DNMT3A) mediate the hypermethylation of the CBX7 promoter, leading to its frequent downregulation in glioblastoma tissues and cell lines." (PMID 39988672, 2025). "In this study, query of the TCGA database revealed that CBX7 is the most significantly downregulated member of the CBX family in glioblastoma compared to normal tissues." (PMID 39988672, 2025). "In summary, these results suggest that CBX7 inhibits the stemness phenotype of glioblastoma cells by downregulating MYH9." (PMID 39988672, 2025). "Next, we overexpressed CBX7 in the tumorigenic glioblastoma cell line U251 and performed RNA sequencing (RNA-seq)." (PMID 39988672, 2025). "This analysis showed that CBX7 mRNA levels were significantly downregulated in glioblastoma compared to normal tissues." (PMID 39988672, 2025).
glioblastoma (continued). "Next, we analyzed the correlation between stemness genes and CBX7 expression in glioblastoma using online clinical data." (PMID 39988672, 2025). "Immunohistochemistry (IHC) analysis of clinical glioblastoma tissue samples revealed that CBX7 expression can serve as an independent prognostic factor for glioblastoma patients." (PMID 39988672, 2025). "Conversely, CBX7 knockdown promoted cell proliferation, colony formation, and significantly enhanced the migration and invasion potential of glioblastoma cells." (PMID 39988672, 2025). "Our current research indicates that CBX7 plays a key role in suppressing the stem-like phenotype of glioblastoma." (PMID 39988672, 2025). "To assess the correlation between CBX7 and glioblastoma tumorigenesis, we implanted second-generation 3D cultures subcutaneously into nude mice and measured CBX7 mRNA expression in the subcutaneous tumors by PCR." (PMID 39988672, 2025). "Our research focuses on elucidating the regulatory mechanisms of CBX7 in GSCs and further identifying and validating its direct target genes in glioblastoma." (PMID 39988672, 2025). "Our findings complement the understanding of the role of CBX7 in the stemness phenotype in glioblastoma." (PMID 39988672, 2025). "In other words Cbx7 augments the Hippo pathway by monitoring the YAP/TAZ dependent transcriptional activity which gets breached in the glioblastoma scenario." (PMID 27291091, 2016). "The balance of CBX7 and CBX8 expression is also known to play an important role in glioblastoma where CBX7 is depleted and CBX8 is abundantly expressed." (PMID 27449098, 2016). "In our study, we demonstrate that Cbx7, yet another polycomb protein is downregulated in glioblastoma and moreover, we prove that the downregulation of Cbx7 is attributed to its promoter hypermethylation." (PMID 27291091, 2016). "Surprisingly, some PRC1 components (BMI1, CBX2, CBX7) were downreglated in glioblastoma compared to normal brain." (PMID 20920292, 2010). "Despite literature reporting that CBX7 suppresses glioblastoma migration through the activation of the Hippo signaling pathway, the potential mechanisms by which it regulates GSCs in glioblastoma remain unclear." (PMID 39988672, 2025). "In conclusion, these data suggest that CBX7 can inhibit stemness in glioblastoma cells." (PMID 39988672, 2025). "To clarify whether CBX7 exerts tumor-suppressive biological functions in glioblastoma, we established CBX7 overexpression and knockdown models based on CBX7 protein levels in glioblastoma cell lines for subsequent studies." (PMID 39988672, 2025). "Furthermore, overexpression of MYH9 in glioblastoma cells reverses the inhibitory effects of CBX7 on migration, proliferation, invasion, and stemness of glioblastoma cells." (PMID 39988672, 2025). "Since the CBX family plays a crucial role in regulating tumor cell stemness, we hypothesized that CBX7 might exert its biological function by regulating the stem cell phenotype in glioblastoma." (PMID 39988672, 2025). "The downstream target genes of CBX7 in glioblastoma remain undefined." (PMID 39988672, 2025). "Additionally, our study revealed that DNMT1 and DNMT3A mediate the hypermethylation of the CBX7 promoter, leading to its frequent silencing in glioblastoma cell lines and primary tumor tissues." (PMID 39988672, 2025). "Functional experiments showed that overexpression of CBX7 significantly inhibited glioblastoma cell growth, colony formation, migration, invasion, and stemness proliferation in vitro, and notably reduced the growth rate of intracranial and subcutaneous tumors in vivo." (PMID 39988672, 2025). "In vitro experiments demonstrated that CBX7 can inhibit glioblastoma cell stemness." (PMID 39988672, 2025). "Chromobox protein homolog 7 (CBX7) can inhibit the progression of various tumors, but its impact on the stem cell-like properties of glioblastoma cells remains unclear." (PMID 39988672, 2025).
glioblastoma (continued). "This made us to elucidate the potential contribution of Cbx7 in glioblastoma biology." (PMID 27291091, 2016). "Based on gene set enrichment analysis (GSEA) of the combined CGGA-GBM and TCGA-GBM datasets, the ssGSEA enrichment score of HALLMARK_STEMNESS (stemness score) was significantly negatively correlated with CBX7 mRNA expression in glioblastoma." (PMID 39988672, 2025). "Likewise, miR-18a plays a malignant role via directly targeting CBX7 in human glioblastoma." (PMID 31709304, 2019). "Here, we reveal that CBX7 interacts with MYH9 to promote its degradation, thereby inhibiting glioblastoma cell stemness." (PMID 39988672, 2025). "We conducted mass spectrophotometry analysis of glioblastoma cells and identified MYH9 as a novel regulatory target of CBX7." (PMID 39988672, 2025). "In this study, we found that CBX7 interacts with MYH9, with Ring1A/B acting as E3 ligases, promoting MYH9 degradation through the ubiquitin-proteasome pathway in glioblastoma." (PMID 39988672, 2025). "Here we reveal that CBX7, as part of the PRC1 complex, promotes MYH9 ubiquitination and degradation, thereby inhibiting the glioblastoma stem cell phenotype, with Ring1A/B serving as E3 ligases." (PMID 39988672, 2025). "CBX7 is an important component of PRC1 and is involved in the development of various cancers, including glioblastoma." (PMID 39988672, 2025). "We found that compared to differentiated glioblastoma cells (DGC), expression of CBX2, CBX3, and CBX5 were upregulated, while CBX1, CBX4, CBX6, CBX7, and CBX8 were downregulated." (PMID 39988672, 2025). "The expression levels of CBX6 and CBX7 are downregulated, and the expression of CBX8 is upregulated in glioblastoma samples, whereas the expression of CBX2 and CBX4 remain unchanged." (PMID 24260522, 2013). "Additionally, we have demonstrated for the first time that CBX7, as part of the PRC1 complex, promotes MYH9 ubiquitination and degradation, inhibiting stemness, migration, invasion, and colony formation in glioblastoma cells." (PMID 39988672, 2025). "Subsequently, a negative correlation between CBX7 mRNA and its methylation levels were observed in the TCGA database, indicating that promoter methylation plays a significant regulatory role in the expression of CBX7 in glioblastoma." (PMID 39988672, 2025). "We show that CBX7 promotes the degradation of myosin heavy chain 9 (MYH9) protein through the ubiquitin-proteasome pathway via the polycomb repressive complex 1 (PRC1) and suppresses the stem-like phenotype of glioblastoma cells by inhibiting the nuclear factor kappa-B (NF-κB) signaling pathway." (PMID 39988672, 2025). "However, of note, CBX7 expression has a negative correlation with advanced tumor aggressiveness and poor prognosis in a wide range of tumor types, such as thyroid, colorectal, pancreas, breast, lung, and glioblastoma (GBM)." (PMID 28460453, 2017). "On the other hand, CBX7 expression level was down-regulated in T98G, but not in U251MG cells glioblastoma cells, when compared to levels in primary astrocytes." (PMID 24260522, 2013).
colorectal cancer (9 papers, 2010 to 2022). A primary or metastatic malignant neoplasm that affects the colon or rectum. "However, several recent studies showed that decrease or loss of CBX7 protein expression correlated with a more aggressive phenotype in pancreatic, thyroid and colorectal cancer, which suggested that CBX7 might act as a potential tumor suppressor." (PMID 20723236, 2010).
lymph node metastasis (9 papers, 2010 to 2023). "CBX7 can act as an oncogene and is positively associated with clinicopathologic features in patients with GC, including clinical stage, lymph node metastasis and age." (PMID 36140750, 2022). "Furthermore, CBX7 was associated with the disease clinical staging, histological differentiation, lymph node metastasis, and vascular invasion." (PMID 33748425, 2021). "Of note, CBX7 was downregulated in N3 samples compared to N1 and N2 samples, suggesting that patients with a low expression of CBX7 harbored more lymph node metastasis." (PMID 36140750, 2022). "The upregulation of CBX7 is related to age, lymph node metastasis and clinical stage, and indicates worse prognosis in GC patients." (PMID 36140750, 2022). "Our results may indicate that FABP4, GISN2, and CBX7 could be considered predictive biomarkers of the occurrence of lymph node metastases in the cancer of the cervix preoperatively, which could be beneficial in the accurate preoperative design therapy." (PMID 38864083, 2023). "Importantly, we found that overexpression of CBX7 correlated with advanced clinical stage and positive lymph node metastasis." (PMID 20723236, 2010). "To further clarify the roles of CBX3, CBX5, and CBX7 in disease progression, we use the UALCAN database to analyze CBX expression in different patients with different disease grades and lymph node metastasis status." (PMID 34966411, 2021). "We found that the majority of lymph node metastases (70.7%, n = 41) did not express CBX7." (PMID 27449098, 2016). "In paraffin-embedded archival gastric tumor samples, there was a significant positive correlation between CBX7 expression with clinical stage and lymph node metastasis (N classification), and a significant negative correlation between CBX7 expression and patients' age." (PMID 20723236, 2010). "However, multivariate Cox proportional hazards model analysis showed that lymph node metastasis, but not CBX7 is an independent prognosis factor." (PMID 20723236, 2010).
B-cell lymphomas (6 papers, 2010 to 2024). "CBX7 promotes T-cell lymphoma, and when sensitized oncogenes are directed to B-cell loci, CBX7 also promotes aggressive B-cell lymphoma, with a presence and latency similar to that of BMI-1." (PMID 34659360, 2021). "Otherwise, CBX7 can initiate T-cell lymphomagenesis and cooperate with c-Myc to produce highly aggressive B-cell lymphomas in the generation of transgenic mice overexpressing CBX7." (PMID 20723236, 2010). "Indeed, it was shown that Cbx7 expression in mice lymphoid compartment can promote T cell lymphomagenesis and, working together with c-Myc, produces aggressive B cell lymphomas by downregulating Ink4a/Arf locus." (PMID 28259135, 2017). "In addition, CBX7 may initiate T-cell lymphomagenesis and cooperate with c-Myc to produce highly aggressive B-cell lymphomas." (PMID 28030829, 2017).
follicular lymphoma (5 papers, 2017 to 2025). Follicular lymphoma is a form of non-Hodgkin lymphoma characterized by a proliferation of B cells whose nodular structure of follicular architecture is preserved. "CBX7 plays a dual role in hematological malignancies, acting as an oncogene in follicular lymphoma and a potential tumor suppressor in CML." (PMID 40175347, 2025). "In follicular lymphoma, CBX7 is upregulated and contributes to lymphomagenesis and leukemogenesis, with its overexpression in hematopoietic stem cells driving the development of these cancers." (PMID 40175347, 2025). "CBX7 could also be a target for follicular lymphoma in the clinic." (PMID 28388562, 2017).
leukemia (5 papers, 2019 to 2024). A malignant (clonal) hematologic disorder, involving hematopoietic stem cells and characterized by the presence of primitive or atypical myeloid or lymphoid cells in the bone marrow and the blood. "When one of the subunits of PRC1, Cbx7, is overexpressed in hematopoietic and progenitor cells, it promotes leukemia." (PMID 39048945, 2024). "We also found that short-term exposure of leukemic cells to CBX7 inhibitors delayed leukemia formation in vivo." (PMID 40552137, 2024). "Most notably, a short ex vivo exposure of primary leukemic cells to CBX7 inhibitors reduced engraftment of leukemia-initiating cells in immunodeficient mice." (PMID 40552137, 2024). "Specifically, the CBX7 protein has been found to be abundantly expressed in hematopoietic stem cells whereas the upregulation of CBX7 induced self-renewal of stem cells and leukemia formation." (PMID 32742466, 2020). "We found MS45224 as the best commercially available CBX7 inhibitor for leukemia treatment." (PMID 40552137, 2024). "Therefore, pharmacological targeting of CBX7 constitutes a novel therapeutic approach for leukemia." (PMID 40552137, 2024). "Because we observed that CBX7 inhibitors impair leukemic cell survival and trigger those cells to differentiate, we wanted to investigate whether CBX7 inhibitors could delay the onset of leukemia in vivo." (PMID 40552137, 2024). "Therefore, CBX7 may constitute a novel therapeutic approach in leukemia." (PMID 40552137, 2024). "Overexpression of Cbx7, one of the PRC1 subunit, in hematopoietic and progenitor cells promoted leukemia." (PMID 31700696, 2019). "Although there is no strong evidence of CBX7 overexpression in leukemia, we do show that leukemic cells have higher CBX7 transcript levels than normal HSPCs." (PMID 40552137, 2024). "Indeed, our data suggest that CBX7 activity is essential for leukemic cells, regardless of their subtype, and, therefore, the antileukemic effect of CBX7 inhibition can most likely be translated to any immature hyperproliferative leukemia type." (PMID 40552137, 2024).
urothelial carcinoma (5 papers, 2013 to 2023). A malignant neoplasm derived from the transitional epithelium of the urinary tract (urinary bladder, ureter, urethra, or renal pelvis). "In urothelial carcinoma, the expression of CBX7 showed a close correlation with high tumor grade 16." (PMID 35342353, 2022).